RELB (RELB proto-oncogene, NF-kB subunit)
Diseases named in the same sentence as RELB in open-access papers (continued):
Sharing a sentence is not in itself a finding about the gene and the disease.
cancer (continued). "Upregulated genes included members of the tumor necrosis factor superfamily (TNFRSF9, TNFRSF11B, and TNFSF8), ABC transporters (ABCB1 and ABCG2), and nuclear factor (NF)-κB-related genes (NFKB2 and RELB), all of which induce stemness in cancer cells." (PMID 28423353, 2017). "Additional reports identified that elevated nuclear RelB in cancer cells promotes tumorigenicity and leads to elevated plasma interleukin-8 levels." (PMID 29371965, 2017). "In any case, our results collectively with the literature warrant further investigation of RelB functions in cancer." (PMID 26147201, 2015). "NF-κB is a transcriptional factor of the Rel family proteins, including p65 (RelA), RelB, c-Rel, p50 (NF-κB1) and p52 (NFκ-B2), which regulates cell proliferation, anti-apoptosis and cytokine secretion in many cancers." (PMID 24481412, 2014). "In breast cancer, RelB stimulates cell proliferation, invasion and increases resistance to anti-cancer therapies." (PMID 25788857, 2014). "With the exception of c-Rel, each subunit was detected in the nucleus of cancer cells: significant nuclear expression of RelB, RelA, p52, and p50 was seen in 26.6, 15.6, 10.7, and 10.5% of cores, respectively." (PMID 16205698, 2005). "NIK expression is the hallmark of non-canonical (p52/RelB) NF-κB activation, a pathway associated with the stem cell phenotype in various cancers, including lung and breast cancers." (PMID 39122708, 2024). "RelB was significantly correlated with DNA methylation in 13 types of cancer." (PMID 37388242, 2023). "Therefore, the goal of this study was to explore the expression profile, prognostic value, methylation level of RelB, and potential relationship between RelB expression and immune-related functions in human pan-cancer." (PMID 37388242, 2023). "In the final, we analyzed the relationship between RelB expression and immune-infiltration cells in human pan-cancer, which suggested RelB could be a promising therapeutic target for cancer immunotherapy." (PMID 37388242, 2023). "In order to check if RelB could be a reliable prognostic biomarker for human cancers, we analyzed the RelB expression in different clinical stages in pan-cancer." (PMID 37388242, 2023). "RelB expression was significantly linked with the relative abundance of CD4 T cells, CD8 T cells, B cells, neutrophils, macrophages and dendritic cells in most cancer types." (PMID 37388242, 2023). "We observed RelB expression was linked with TMB and MSI in some cancer types." (PMID 37388242, 2023). "As shown, the expression of NFKB1, NFKB2, REL, RELA, and RELB varied in different cancer types." (PMID 35036435, 2022). "When RelB binds to a promoter of a downstream target, its partners or regulators can be activated, which subsequently triggers intracellular signaling cascades that promote the aggressive growth of cancer cells." (PMID 35742868, 2022). "Similarly, RELB (selected for 17 of 18 cancer types), which is part of the NF-κB complex, also regulates PD-L1 expression and inflammation." (PMID 34430923, 2021). "Interestingly, RELB, a feature in this signature, had previously demonstrated sexually dimorphic expression upon cancer treatment." (PMID 34766125, 2020). "The NF-κB family of transcription factors includes RelA (p65), RelB, c-Rel, NF-κB1 (p50/p105), and NF-κB2 (p52/p100), which play important roles in inflammation, cell proliferation and differentiation, immune responses, and cancer 31-33." (PMID 32913455, 2020). "A possible explanation for the translational value of RelB may lie on the functional connection of RelB with cancer cell growth, migration, and invasion." (PMID 31586084, 2019). "Furthermore, ChIP-sequencing analysis for p52 and/or RelB would also allow for us to identify additional bona fide binding sites in cancer cells." (PMID 30096845, 2018).
cancer (continued). "However, the non-canonical NF-κB pathway showed increased signalling from day 3, and NIK, p52, and RelB were increased in the cancer group." (PMID 28350008, 2017). "CRM1 is known to export RelA from the nucleus, a mechanism that could explain the observed cytoplasmic localization of RelA in our samples and that could render RelB the only nuclear NF-κB transactivator in laryngeal and other cancers." (PMID 29371965, 2017). "Moreover, that RelB assessed at the time of diagnosis can predict the survival of patients with this cancer type." (PMID 29371965, 2017). "Since we previously found that loss of the ARNT isoforms leads to modification of RelB DNA binding, we sought to investigate whether the ARNT isoforms depend on RelB for regulating cancer cell proliferation." (PMID 26909609, 2016). "Interestingly, a recent study demonstrated that ionizing radiation induces RelB to activate Bcl-xL in cancer cells." (PMID 26735768, 2016). "Here, we demonstrate that RelB is constitutively activated in approximately 40% of MM cases, a much higher frequency than expected based on evaluation of the alternative NF-κB signaling cascade activation by cancer genomic approaches." (PMID 23555623, 2013). "It will be of interest in future studies to define whether RNASET2 derived from cancer cell, could influence, the NK-κB pathway by changing the RELB expression levels in cells of the monocyte/macrophage lineage." (PMID 21646684, 2011). "Similarly, there was also a trend towards higher RelB nuclear staining in high-grade cancer tissue cores." (PMID 16205698, 2005). "Interestingly, overexpression of RelB could be a protective factor in three cancer types (SARC, SKCM, BRCA)." (PMID 37388242, 2023). "Additionally, RelB had been demonstrated to be involved in cancer development and progression, and RelB might determine the response of cancer treatments." (PMID 37388242, 2023). "Interestingly, RT generates ROS, and RT also induces RelB in both normal and cancer cells." (PMID 35742868, 2022). "However, whether RelB serine 472 phosphorylation can participate in the invasiveness of cancer cells is currently unknown but is nevertheless worth further investigation." (PMID 27153093, 2016). "While previous reports show that RelB could intervene in potential tumorigenic cell processes as proliferation, invasion and resistance to several anti-cancer therapies, this is the first study to show that the alternative NF-κB pathway can induce autophagy in an anchorage-free assay." (PMID 25788857, 2014). "From a clinical perspective, TPM3P9 expression is upregulated in cancer tissues and is significantly correlated with the expression of TCF7L2-L and RELB." (PMID 39865075, 2025). "Remarkably, the deficiency of DDX5 in hepatocytes activates the interconnected Wnt/β-catenin-NIK/p52/RelB- and NRF2 pathways, all relevant to cancer." (PMID 39122708, 2024). "Remarkably, genes that have been reported not to be associated with PD-1 signaling or other inhibitory T cell functions, such as RELB and HSP1, were significantly lower in the NR cancer patients." (PMID 38254179, 2024). "To further define the role of RelB in the different responses of cancer cells vs. normal cells against radiation or radiation with P-AscH− treatment, we used RelB CRISPR/Cas9 KO plasmid in MIA PaCa-2 cells to generate RelB knockout cells (MIA RelB KO)." (PMID 33923601, 2021). "To provide an overview on the occurrences of distinct NF-κB subunits in cancer subtypes, we assessed the overexpression of the NF-κB subunits RELA, RELB, and c-REL in human cancers by database mining, using COSMIC." (PMID 29673141, 2018). "The activity of RelB and NFKB2/p52 has been demonstrated in numerous cancer types, and they regulate a diverse set of genes." (PMID 29874793, 2018).
cancer (continued). "OC numbers in the bones of RelB-/- mice are normal in vivo, while RANKL-induced OC formation from RelB-/- myeloid progenitors is impaired in vitro, and cancer-induced osteolysis is reduced in RelB-/- mice in vivo." (PMID 26287732, 2015). "Our analysis showed that AATF, LGALS3, and SRC are up regulated in 8/13 of cancer models, and CDC2L2, E2F6, LGALS9, PDCD8, RELB, TRADD, and TRAF2 in 7/13." (PMID 19402918, 2009). "Besides, we investigated the correlation of RelB expression with the relevant prognostic indictors including OS, PFI, DFI, DSS in pan-cancer." (PMID 37388242, 2023). "Although increasing evidence suggested that RelB played an important role in the oncogenesis of most cancer types, a comprehensively systematic pan-cancer analysis of RelB had not yet been performed." (PMID 37388242, 2023). "When comparing the candidates to the non-candidate genes (those non-NFκB/TNF hallmark genes receiving no votes across all cancer types), the candidates displayed higher similarity to the canonical pathway genes TNF, RELA, NFKB1, and RELB." (PMID 37475016, 2023). "Because the normal tissue controls were very limited in some cancer types, we then combined TCGA data and GTEx data together to investigate the RelB expression between cancer tissues and the corresponding normal tissues." (PMID 37388242, 2023). "We showed that the canonical signaling pathway, which is driven by RELA, and the non-canonical pathway, which is driven by RELB, affect cancer cell proliferation and the cancer stem cell maintenance, respectively." (PMID 37175530, 2023). "We tested whether the transcription factors that have been reported to induce PD-L1 in other cell or cancer types, including CEBPβ, NRF2 and RelB induced PD-L1." (PMID 37985999, 2023). "In comparison, the non-canonical dimer p52/RelB is understudied in tumorigenesis and cancer therapy." (PMID 35742868, 2022). "We revealed that RelB constitutive activation in OxPhos-DLBCL cells programs DLBCL cells towards oxidative energy metabolism, indicating that RelB impacts on energy metabolism in these cancer cells." (PMID 35203557, 2022). "Although P-AscH− with radiation decreases RelB in cancer cells vs. normal cells, the knockout of RelB does not radio-sensitize PDACs." (PMID 33923601, 2021). "Various members of the NF-κB family are constitutively activated in many cancers via one of the two pathways: the canonical pathway involving RelA, NF-κB1 p50 and c-Rel and the non-canonical pathway engaging RelB and NF-κB2 p52." (PMID 32122395, 2020). "Nevertheless, the RelB-based noncanonical NF-κB pathway in cancer progression remains to be elucidated." (PMID 32807176, 2020). "Activation of the noncanonical NF-κB transcription factors, namely RelB and p52, can support the growth of several cancer types." (PMID 29874793, 2018). "KRAS-mutant cancer cells are shown to respond to host provided IL-1β in the pleural space by increasing non-canonical IKKα-RelB pathway activity." (PMID 29445180, 2018). "While the clinical potential of RelB seems low, this does not preclude a functional role for this alternative NF-κB pathway in cancer or even as a therapeutic target." (PMID 26186215, 2015). "Conversely, we found no loss of ERBB2, EGFR, ABL1, RELA, and RELB transcript in c-MYC-destabilized cells compared to controls, and the 3′UTRMYC1-18-treated cancer cells tended to restore MYC expression towards the normal female mammary epithelial expression levels." (PMID 39123391, 2024). "Importantly, our studies show that upon RT, BET-mediated H2O2 production triggers RelB-mediated MnSOD protein expression in non-cancer cells but not in PCa cells." (PMID 35742868, 2022). "In contrast, to our knowledge the role of the alternative RelB NF-κB subunit in cancer cell metabolism has not yet been reported, and whether it may impact on DLBCL OxPhos status for survival remains an unanswered question." (PMID 35203557, 2022).
cancer (continued). "In addition to well-documented RelA-based canonical NF-κB pathway in cancer development, the present study demonstrates that the RelB-based noncanonical NF-κB pathway plays a crucial role in advanced BCa as followed by ER functional decline." (PMID 32807176, 2020). "Indeed, KRAS-mutant cancer cells displayed non-canonical endogenous NF-κΒ activity evident by enhanced nuclear localization and/or DNA-binding activity of RelB, ΙκΒβ, and ΙΚΚα, which was further inducible by exogenous IL-1β." (PMID 29445180, 2018). "Importantly, non-canonical NF-κΒ utilization by KRAS-mutant cancer cells was IKΚα driven, involved RelB activation, and was required for MPE." (PMID 29445180, 2018). "Moreover, we provide novel evidence that mutant KRAS is indirectly responsible for non-canonical NF-κB activation, which is IKKa and RelB based, via sensitization of cancer cells to host IL-1β." (PMID 29445180, 2018). "Indeed, the noncanonical NF-κB transcription factors RelB and p52 were recently shown to induce APOBEC3B expression in some cancer cells." (PMID 29874793, 2018).
infection (34 papers, 2008 to 2024). The state of being infected such as from the introduction of a foreign agent such as serum, vaccine, antigenic substance or organism. "We aimed to clarify the contribution of RelB to human immunity by screening our database of >25,000 exomes from patients with severe infections, searching for rare predicted deleterious biallelic variants of RELB." (PMID 39231201, 2024). "This indicates that infection with M. tuberculosis Δppe38-71 causes translocation of RelB/p50 complexes, which has been shown to be associated with anti-inflammatory responses." (PMID 34276695, 2021). "We could show that dampening of the pro-inflammatory response is associated with activation of a RelB/p50 pathway, while the canonical inflammatory pathway is active during infection with wild type M. tuberculosis CDC1551." (PMID 34276695, 2021). "In contrast, infection by M. tuberculosis Δppe38-71 stimulated the signalling of a different NF-kB pathway where RelB and p50 are translocated to the nucleus." (PMID 34276695, 2021). "Research studies reported that airborne PM decreased the ability of pulmonary macrophages to effectively mount a defense against infection, which would last at least a week post-exposure via RelB activation." (PMID 33087097, 2020). "siRNA knockdown of IKKα resulted in a significant reduction in the DNA-binding abilities of nuclear RelB in response to infection with P. histicola (p<0.001)." (PMID 33031374, 2020). "IE1, a promiscuous transactivator of NFκB pathway constituents and their downstream targets during infection, has been implicated in the upregulation of p65, IL-6, TNF-α and IL-8 as well as the induction of p52/RelB heterodimer binding activity in the nucleus." (PMID 30134546, 2018). "A UL26 deletion mutant virus is severely attenuated, and UL26 has been shown to be necessary to inhibit IKK complex phosphorylation and RelB translocation during infection." (PMID 30134546, 2018). "Initial localization studies indicate that mCMV infection changed the cell-specific expression of FN, NF-κB2, RelA, RelB, and Shh and Smad7 proteins." (PMID 18371224, 2008). "Consequently, DC-specific RelB knockout animals fail to mount protective Th2-dominated immune responses in the intestine after infection with Heligmosomoides polygyrus bakeri." (PMID 39443450, 2024). "Overall, these results suggest that there is a B cell-intrinsic requirement of RelB for the generation of class-switched memory B cells and Ab-secreting cells, accounting for the severe hypogammaglobulinemia and recurrent infections observed in P1 (pretransplantation) and P2." (PMID 39231201, 2024). "Finally, our results suggest a role for PPE38-controlled PE/PPE proteins of M. tuberculosis in infection by modulating the inflammatory response through nuclear factor kappa B (NF-kB) signalling via the RelB pathway." (PMID 34276695, 2021). "However, significant levels of nuclear RelB were observed in response to infection with P. histicola (2 hours, p<0.001) with a reduction at 4 hours post infection compared to baseline controls." (PMID 33031374, 2020). "To assess whether non-canonical NF-κB signaling could be related to the more severe pathology observed in Myd88−/− mice upon infection with H. felis, we first evaluated nuclear translocation of RelB into the nucleus of gastric epithelial cells." (PMID 31065023, 2019). "After infection, nuclear localization of P50, p52, RelA, and RelB was detected." (PMID 28346502, 2017). "Taken together, it is conceivable that HIV-1 Tat protein may induce G1 arrest through the downregulation of RelB expression while using the available RelB protein to promote bypassing cellular restrictions in the early phase and promote gene expression in the late phase of infection." (PMID 38203551, 2023).